MAST4 (microtubule associated serine/threonine kinase family member 4)
Synonyms: KIAA0303
Tractability: Small molecule: a high-quality ligand is known; it belongs to a druggable protein family. PROTAC: ubiquitination databases record sites on it; a small molecule that binds it is known.
Target class: Enzyme; AGC protein kinase group; Protein Kinase; Kinase; AGC protein kinase MAST family
Gene: Protein-coding gene on chromosome 5 (66,596,380 to 67,169,593, forward strand). Ensembl gene ENSG00000069020.
Subcellular location: Cytoplasm
Subcellular location (Human Protein Atlas): Cytosol; Nucleoplasm
Gene Ontology:
Molecular function: protein serine/threonine kinase activity; ATP binding; magnesium ion binding; protein kinase activity; protein serine kinase activity
Biological process: cytoskeleton organization; intracellular signal transduction; developmental process
Cellular component: microtubule cytoskeleton; cytoplasm
Genetic constraint (gnomAD): Loss-of-function variants: 75 observed, 137.62 expected, observed/expected ratio (o/e) 0.54, 90% interval 0.45 to 0.66. The upper end of that interval is the gene's LOEUF score, 0.66, which puts it in group 2 of 6, group 1 being the genes least tolerant of losing a copy. Missense variants: 3,068 observed, 3,249.7 expected, observed/expected ratio (o/e) 0.94, 90% interval 0.92 to 0.97. Synonymous variants: 1,447 observed, 1,322 expected, observed/expected ratio (o/e) 1.09, 90% interval 1.05 to 1.14.
Homologues: Orthologues: chimpanzee MAST4 (99% identical), macaque MAST4 (96% identical), rat Mast4 (82% identical), mouse Mast4 (82% identical), rabbit MAST4 (77% identical), guinea pig MAST4 (76% identical), pig MAST4 (74% identical), dog MAST4 (73% identical), tropical clawed frog mast4 (56% identical), Drosophila melanogaster dop (27% identical), Caenorhabditis elegans kin-4 (22% identical), Caenorhabditis elegans wts-1 (6% identical), and 3 more. Paralogues in human: MAST2 (38% identical), MAST1 (34% identical), MAST3 (31% identical), LATS1 (9% identical), LATS2 (9% identical), DMPK (7% identical), SGK1 (7% identical), SGK3 (6% identical), STK32C (6% identical), MASTL (6% identical), STK32B (5% identical), SGK2 (5% identical), and 1 more.
Diseases named in the same sentence as MAST4 in open-access papers:
MAST4 is named in the same sentence as 30 diseases in open-access papers, as found by Europe PMC text mining. Sharing a sentence is not in itself a finding about the gene and the disease. The quoted sentences say what the papers report.
breast carcinoma (6 papers, 2015 to 2024). "For example, we identified a novel breast cancer risk gene, MAST4, with expression that was repressed by glucocorticoids in cells carrying the risk genotype, repression that correlated with MAST4 expression in breast cancer and treatment outcomes." (PMID 36399508, 2022). "For example, we conducted a series of in-depth functional validation studies using breast cancer cell lines for a breast-cancer-risk SNP that was discovered in LCLs to be a PGx-eQTL with MAST4." (PMID 36399508, 2022). "Underexpression of MAST4 is associated with survival in breast cancer patients." (PMID 38612866, 2024). "Although the function of MAST4 in breast cancer is unknown, it may be a novel risk gene since its expression was significantly repressed in breast tumor tissue when compared with normal breast tissue (P < 0.0001)." (PMID 36399508, 2022). "Of interest, both Tctex-1 and MAST4 have been proposed to be potential prognosis markers of breast cancer, because of their up-regulated expression in human primary breast cancer tissues." (PMID 37726137, 2023). "Specifically, the rs1697139-G/G genotype was associated with decreased MAST4 expression after exposure to cortisol, a hormone that promotes breast cancer heterogeneity and metastasis, which might have led to the increased risk for breast cancer observed in the original GWAS." (PMID 36399508, 2022). "Preliminary validation of 3 potential markers (ECM1, MAST4 and filaggrin) identified was performed in breast cancer cell lines by Western blotting." (PMID 26544852, 2015). "One potential marker MAST4 was further validated in human breast cancer tissues as well as individual human breast cancer urine samples with immunohistochemistry and Western blotting, respectively." (PMID 26544852, 2015). "Moreover, ECM1, MAST4, FLG, and MAST4 are implicated as potential biomarkers for the preliminary indication of breast cancer presence." (PMID 38250812, 2023). "Furthermore, extracellular matrix protein 1 (ECM1), microtubule-associated serine/threonine kinase family member 4 (MAST4), and Filaggrin (FLG) exhibit heightened levels in the urine of breast cancer patients." (PMID 38250812, 2023). "Moreover, suppression of MAST4 was found to be correlated with treatment outcome in breast cancer." (PMID 38612866, 2024). "In breast cancer, non-invasive detection through urinary biomarkers, such as MMP9, NGAL, CD63, ECM1, MAST4, and Filaggrin, offers insights into disease progression." (PMID 38250812, 2023). "To interrogate the causal relationship between this SNP locus and MAST4 gene expression in breast cancer cells, we used CRISPR/Cas9 to delete the SNP region and measured GR-dependent MAST4 mRNA expression." (PMID 36399508, 2022).
frontotemporal dementia (3 papers, 2017 to 2024). Frontotemporal dementia (FTD) comprises a group of neurodegenerative disorders, characterized by progressive changes in behavior, executive dysfunction and language impairment, as a result of degeneration of the medial prefrontal and frontoinsular cortices. "MAST4 codes for a microtubule protein part of the serine/threonine kinase family, with differential expression in frontotemporal dementia." (PMID 30279459, 2020).
multiple myeloma (3 papers, 2023 to 2025). "MAST4 was identified as an estrogen response gene that was upregulated in female patients with multiple myeloma (MM) associated with low osteolytic lesions." (PMID 37569286, 2023). "However, MAST4 has notable associations with bone differentiation, osteolytic lesions, and multiple myeloma." (PMID 40299535, 2025). "Estrogen signaling negatively regulates multiple myeloma-associated bone lesions through MAST4." (PMID 38612866, 2024). "This MAST kinase-dependent inhibition of PTEN activity was also observed in multiple myeloma cell lines, where knockdown of MAST4 leads to reduced PTEN activity and increased activity of proteins involved in the mTOR signaling pathway." (PMID 37569286, 2023).
developmental delay (2 papers, 2023 to 2025). "De novo variants in MAST4 are emerging as important genetic contributors to neurodevelopmental disorders, typically presenting with global developmental delay and white matter abnormalities." (PMID 40656202, 2025). "In the present study, we described three de novo heterozygous missense MAST4 variants in four unrelated patients with IS and varying levels of developmental delays." (PMID 36910266, 2023). "Here, we identified three heterozygous missense MAST4 variants in four unrelated patients with a spectrum of IS and varying developmental delays." (PMID 36910266, 2023). "This study aims to prove that the de novo variants in MAST4 gene are associated with neurodevelopmental disorders (NDD) with developmental delay (DD) and infantile spasm (IS) and to determine the genotype-phenotype correlations." (PMID 36910266, 2023). "Our results revealed that the variants of MAST4 gene might lead to neurodevelopmental disorders with developmental delay and infantile spasm." (PMID 36910266, 2023). "Here, we report a pediatric case featuring global developmental delay (GDD) and a novel MAST4 variant." (PMID 40656202, 2025). "We report a Chinese child with global developmental delay (GDD) and a novel MAST4 variant, further delineating the genotype-phenotype correlations for this gene." (PMID 40656202, 2025). "Unlike MAST1 variants, which are associated with megalencephaly and corpus callosum anomalies, our patient's MAST4 variant correlates with delayed myelination and developmental delay, without structural malformations." (PMID 40656202, 2025).
epilepsy (2 papers, 2025). A brain disorder characterized by episodes of abnormally increased neuronal discharge resulting in transient episodes of sensory or motor neurological dysfunction, or psychic dysfunction. "To summarize, MAST4 variants exhibit remarkable pleiotropy, contributing to neurodevelopmental disorders with epilepsy, enamel defects, cancer metastasis, MDS risk stratification, and chromosomal rearrangements in malignancies." (PMID 40656202, 2025). "Two of the regions identified in the GWAS (on chromosomes 2 and 8) passed the Bonferroni-adjusted threshold for statistical significance, accounting for multiple testing, and the region on chromosome 2 implicated a gene with compelling candidacy for epilepsy (MAST4)." (PMID 40043055, 2025). "Clinical evidence further implicates MAST4 in NDDs, epilepsy, and hippocampal malformations, though the phenotypic spectrum remains incompletely defined." (PMID 40656202, 2025).
infantile spasms (2 papers, 2023 to 2025). A rare epilepsy syndrome characterized by onset of epileptic spasms in infants between 2 and 12 months of age, and rarely up to 24 months. "Together with the bioinformatic analysis, our results support the possibility that MAST4 relates to neurodevelopmental disorders with infantile spasms as a promising novel pathogenic gene." (PMID 36910266, 2023). "Thus, MAST4 variants should be considered the potential candidate gene in patients with neurodevelopmental disorders clinically marked by infantile spasms." (PMID 36910266, 2023). "The absence of infantile spasms in our case suggests variable expressivity, necessitating further functional studies to assess the variant's pathogenicity and MAST4's neurobiological mechanisms." (PMID 40656202, 2025).
acral melanoma (1 paper, 2025). "In oncology, variants in MAST4 have been implicated in the progression of acral melanoma, potentially facilitating tumor cell metastasis through alterations in adhesion, motility, and invasiveness." (PMID 40656202, 2025).
asthma (1 paper, 2022). "The other protein upregulated during asthma exacerbation was the estrogen-responsive protein microtubule-associated serine/threonine kinase family member 4 (MAST4)." (PMID 36359743, 2022). "Although it has mainly been associated with central nervous system diseases and tumors, MAST4 is also related to asthma pathogenesis." (PMID 36359743, 2022). "Two proteins were regulated by the disease status; leucine-rich repeats and calponin homology domain-containing 4 (Lrch4) and microtubule-associated serine/threonine-protein kinase 4 (MAST4) were upregulated during asthma exacerbation." (PMID 36359743, 2022). "The diagnostic potential of Lrch4 and MAST4 as biomarkers and the involvement of these proteins in asthma pathophysiology require further investigation." (PMID 36359743, 2022). "In patients with mild asthma, its gene expression increases in the sputum after an aerosol allergen bronchoprovocation, and computational analysis revealed that MAST4 methylation is involved in the regulation of ASM response to interleukins." (PMID 36359743, 2022).
Hypertension (1 paper, 2021). The presence of chronic increased pressure in the systemic arterial system. "In this study, a GWAS using TWB data to test the association of SNPs with hypertension reported 6 SNPs (rs1458038 in FGF5, rs3796605 in FGF5, rs455938 in MAST4, rs10866754 in CTC-535M15.2, rs648435 in APHGAP42, and rs2018159 in APHGAP42) to be significantly associated (P < 5e-6) with hypertension." (PMID 34901208, 2021).
Infertility (1 paper, 2023). "Mast4 KO mice showed infertility with Sertoli cell‐only syndrome and reduced sperm count." (PMID 36592615, 2023).
myelodysplastic syndrome (1 paper, 2025). A clonal hematopoietic disorder characterized by dysplasia and ineffective hematopoiesis in one or more of the hematopoietic cell lines. "Additionally, MAST4 expression levels were integrated into kinase profiling for myelodysplastic syndromes (MDS), demonstrating prognostic value for disease progression risk stratification and therapeutic target responsiveness." (PMID 40656202, 2025).
prostate carcinoma (1 paper, 2025). A carcinoma that arises from epithelial cells of the prostate gland. "In prostate cancer research, MAST4 has been identified as a participant in chromosomal translocations within the 5q region of the VCaP cell line, a process driven by chromothripsis." (PMID 40656202, 2025).
Sertoli Cell-Only Syndrome (1 paper, 2023). A type of male infertility in which no germ cells are visible in any of the biopsied SEMINIFEROUS TUBULES (type I) or in which germ cells are present in a minority of tubules (type II). "In addition, the knockdown of MAST4 reveals its role in spermatogenesis as it leads to decreased testes size and sperm number and the typical phenotype of Sertoli cell-only syndrome (SCO)." (PMID 37569286, 2023). "Knockout of MAST4 results in a reduced sperm number and the typical phenotype of SCO (Sertoli cell-only syndrome), which represents a form of male infertility." (PMID 37569286, 2023).
triple-negative breast carcinoma (1 paper, 2022). An invasive breast carcinoma which is negative for expression of estrogen receptor (ER), progesterone receptor (PR), and human epidermal growth factor receptor 2 (HER2). "We found that the SNP behaved in a similar fashion in MDA-MB-231, a triple negative breast cancer cell line, in terms of its interaction with glucocorticoids and the subsequent impact on MAST4 expression." (PMID 36399508, 2022).
tumor (6 papers, 2017 to 2025). "Previous studies have reported upregulation of ANXA2 and HIF1A in MM, whereas MAST4 exhibits tumor-suppressive downregulation." (PMID 41403951, 2025). "LRP1B and ROBO2 are tumor suppressors, but FGF13, MAST4 and SPHKAP have not been associated with cancer development." (PMID 29117265, 2017). "Notably, a weak but significant correlation between MAST4 and MAPT gene expression (r = 0.37, p = 0.0001) was depicted in tumor samples but not in normal tissues." (PMID 37835564, 2023).
cancer (4 papers, 2017 to 2025). A tumor composed of atypical neoplastic, often pleomorphic cells that invade other tissues. "This highlights MAST4's potential role in contributing to genomic instability, as chromosomal translocations are a form of chromosomal instability that can lead to cancer development." (PMID 40656202, 2025). "However, obtaining cancer tissues from PDAC is clinically challenging, and developing more clinically convenient markers, such as blood MAST4, is necessary." (PMID 38612866, 2024). "ROBO2 is also a candidate tumor suppressor gene; thus far, there is no clear evidence that FGF13, MAST4 and SPHKAP are associated with cancer development." (PMID 29117265, 2017).
infection (2 papers, 2022). The state of being infected such as from the introduction of a foreign agent such as serum, vaccine, antigenic substance or organism. "There was an increase in MAST4, FABP1, and KLKB1 levels that lasted until 18 h after LASV infection, whereas increased concentrations of IGFBP3 lasted until 48 h after infection." (PMID 35337059, 2022).
neurodevelopmental disorder (2 papers, 2023 to 2025). A behavioral and cognitive disorder with onset during the developmental period that involves impaired or aberrant development of intellectual, motor, or social functions. "Together, these findings provide strong evidence for the pathogenic potential of this de novo MAST4 variant in the patient's neurodevelopmental disorder." (PMID 40656202, 2025). "De novo variants in MAST4 are increasingly implicated in neurodevelopmental disorders (NDDs), but the associated phenotypic spectrum remains incompletely characterized." (PMID 40656202, 2025). "Through a systematic review of PubMed literature using the search term “MAST4 gene variant”, we identified seven relevant publications, including two studies definitively linking MAST4 variants to neurodevelopmental disorders." (PMID 40656202, 2025). "Summary of MAST4 de novo missense variants identified in neurodevelopmental disorders." (PMID 36910266, 2023).
neurologic disease (2 papers, 2017 to 2023). "Given that many other genes of the MAST family are highly correlated with neurological disorders, we hypothesized that MAST4 is also associated with it." (PMID 36910266, 2023). "However, there are only a few reports on the association between MAST4 and neurological diseases, and the genotype-phenotype correlation needs to be clarified." (PMID 36910266, 2023). "AICD binding to the MAST4 promoter was lower in late-onset AD brains compared to control cases (no neurologic disease) and FTD brains, which was accompanied by less MAST4 mRNA and protein abundance." (PMID 29066835, 2017).
MAST4 also shares sentences with these, for which no sentence is quoted: pituitary adenoma (2 papers); atherosclerosis (1); breast tumor (1); central nervous system diseases (1); ductal carcinoma in-situ (1); invasive breast carcinoma (1); Obesity (1); Pancreatic Ductal Carcinoma (1); pituitary tumor (1); preeclampsia (1); sarcoma (1).